IL17F (interleukin 17F)
Diseases named in the same sentence as IL17F in open-access papers (continued):
Sharing a sentence is not in itself a finding about the gene and the disease.
multiple sclerosis (14 papers, 2013 to 2024). A progressive autoimmune disorder affecting the central nervous system resulting in demyelination. "The aim was to investigate the association of IL-17F (rs763780) SNP with the development of multiple sclerosis (MS) in a cohort of Egyptian patients and to evaluate the effect of this polymorphism on the disease course." (PMID 38871733, 2024). "Moreover, IL-17F is associated with relapse in multiple sclerosis, and IL-17A does not show that correlation, which is quite different from animal models." (PMID 28210632, 2017). "For example, psoriatic lesions appear to have upregulation of both IL-17A and IL-17F, while upregulation of IL-17A, but not IL-17F have been noted in multiple sclerosis brain biopsy." (PMID 37115755, 2023).
Arthritis (13 papers, 2011 to 2025). Inflammation of a joint. "We also determined the concentrations of the cytokines IL-6, IL-10, IFNγ, TNFα, IL-17A, IL-17F, and IL-22 in serum samples of the arthritis patients." (PMID 40806470, 2025). "The objective was to determine the variability in expression of IL-17A, IL-17F and their receptors IL-17RA and IL-17RC in the synovia of patients with arthritis." (PMID 25146432, 2014). "Although IL-17A and IL-17F have been reported to be associated with collagen-induced arthritis, and arthritis in experimental animal models, there is no study about relationship between rs2275913 (IL-17A SNP) and rs763780 (IL-17F SNP) with OA risk." (PMID 30658595, 2019). "The heterogeneous expression patterns of IL-17A, IL-17F and their receptors could perhaps explain the limited clinical response observed in clinical trials in which IL-17A in arthritis is targeted, as many patients exhibit very low IL-17 levels at the site of inflammation." (PMID 25146432, 2014). "Since the severity of K/BxN serum-induced arthritis in their IL-17R deficient mice is similar to that in our IL-17A KO mice, IL-17A may have the dominant role in the IL-17 family members for arthritis induction, although possible important role of IL-17F cannot be excluded." (PMID 23671588, 2013). "Interestingly, the balance of serum IL-17A/IFNγ showed a trend to be increased (P = 0.09) at D44 if P. gingivalis oral infection was present in mice developing arthritis in the CFA/CII group compared with CFA/CII alone, and a nonsignificant trend in IL-17F/IFNγ ratios." (PMID 24456966, 2013).
fungal infections (13 papers, 2009 to 2025). "Il17f encodes one of the 6 members of the IL-17 family known to control bacterial and fungal infections." (PMID 41229427, 2025). "Furthermore, T-lymphocytes and Th17-associated cytokines (defective IL-17A, IL-17F, and IL-22 responses to Candida albicans antigens) responsible for the defense against fungal infection emerged from an early age." (PMID 38673639, 2024). "Interleukin-17A (IL-17A) and Interleukin-17F (IL-17F) are pro-inflammatory cytokines that play crucial roles in the immune system, particularly in host defense against bacterial and fungal infections." (PMID 39335657, 2024). "In general, IL-17A and IL-17F play important roles in chronic inflammation and autoimmunity, controlling bacterial and fungal infections, and signaling mainly through activation of the nuclear factor-kappa B (NF-κB) pathway." (PMID 37600764, 2023). "While they beneficially mediate resistance to extracellular bacterial and fungal infection via enhanced mucosal production of mucus and antimicrobial peptides, IL-17A and IL-17F are also involved in several autoimmune disorders." (PMID 32010094, 2019). "Such a role for IL-17A, the founding member of this family, as well as for IL-17F during bacterial and fungal infections has been largely recognized." (PMID 22577359, 2012). "Th17-type T cells, which produce IL-17, IL-17F, and IL-22, are thought to be important for inflammatory responses and the control of bacterial and fungal infections at mucosal surfaces." (PMID 19360100, 2009). "The IL‐17 family of cytokines consists of six groups: IL‐17A, IL‐17B, IL‐17C, IL‐17D, IL‐17E and IL17‐F, which are involved in the development of autoimmunity, inflammation, tumours, host defences against bacterial and fungal infections, and mucosal host defence mechanisms." (PMID 38363001, 2024). "Although IL-17A and IL-17F are highly homologous, they perform distinct functions: IL-17A plays important roles in inflammation, autoimmunity, and host defenses against bacterial and fungal infections; whereas IL-17F is mainly involved in mucosal host defense mechanisms." (PMID 34733288, 2021). "IL-17F, produced by Th17 helper T cells, type 3 innate immune cells (ILCs), γδT cells, NK T cells, and CD8+ T cells, and by activated monocytes is a pro-inflammatory cytokine involved in host defense against bacterial and fungal infection." (PMID 32625209, 2020). "Th17 cells can directly activate the local immune response by secreting cytokines, such as IL-17A and IL-17F, which promote the production of various inflammatory mediators (such as IL-6 and TNF-α), thus increasing the intensity of the inflammatory response against bacterial or fungal infections." (PMID 39794999, 2024). "However, this patient did not carry any variants in CARD9, IL17RA, L17RC, IL17F, STAT1, DOCK8, MALT1, or TRAF3IP2 genes that can explain the susceptibility to a severe and invasive fungal infection." (PMID 35091979, 2022).
inflammatory bowel disease (13 papers, 2012 to 2025). A spectrum of small and large bowel inflammatory diseases of unknown etiology. "As pro-inflammatory cytokines, IL-1β and IL-17F have been implicated in the disease pathogenesis, such as inflammatory bowel disease and celiac disease in humans." (PMID 29311620, 2018). "The expression levels of IL-17A and IL-17F are significantly elevated in the inflamed mucosa of patients with inflammatory bowel disease (IBD)." (PMID 40143073, 2025). "Interleukin 17F is closely related to IL-17A and its role in the development of inflammatory bowel disease remains not well-established." (PMID 32724117, 2020). "In laminar propria lymphocytes of inflammatory bowel disease patients, LIF-activated STAT4 inhibits activation of the STAT3-dependent Il17a/Il17f promoter, while in intestinal epithelial cells, LIF bypasses abnormally low STAT4 levels and induces YAP gene expression by activating STAT3." (PMID 33505963, 2020). "They suggested that there is the presence of a potential therapeutic role for combined blockage of IL17A and IL17F in the treatment of inflammatory bowel disease, rather than blocking either cytokine alone." (PMID 26083022, 2015).
gastric cancer (12 papers, 2014 to 2024). A primary or metastatic malignant neoplasm involving the stomach. "The polymorphisms of IL-17A G197A (rs2275913) and IL-17F A7488G (rs763780) has been associated with susceptibility to various types of proinflammatory diseases and gastric cancer." (PMID 32616024, 2020). "A 1:1 matched case-control study was conducted to analyze the association between three common interleukin (IL)-17A and IL-17F single nucleotide polymorphisms (SNPs) and the risk of developing gastric cancer." (PMID 25663919, 2015). "The IL-17F rs763780T>C polymorphism was also significantly associated with gastric cancer development." (PMID 25147431, 2014). "Also, IL-17A and IL-17F were investigated in gastric cancer risks and the association of each single nucleotide polymorphism (SNP) with subtypes of gastric cancer according to its clinicopathological features and their roles in prognosis." (PMID 32616024, 2020). "CCL5, CCL22, CCL21, CCL2, and CCL15 were correlated with effector memory CD4 T cell in T1/T2 stage gastric cancer, and the number of cells was associated with the expression of IL3, IL17F, IL18, IL22, and IL31." (PMID 33426088, 2020). "Various studies have demonstrated that IL-17A and IL-17F may be involved in the development of gastric cancer, however, the results were unclear." (PMID 25663919, 2015). "Similarly, The IL-17F H161R genetic variation has also been studied in relation to various other disorders., including functional dyspepsia (FD), BD, chronic fatigue syndrome (CFS) or gastric cancer FD and H. pylori-infected patients." (PMID 37751416, 2023).
candidiasis (10 papers, 2011 to 2025). Infection with the organism Candida. "Similarly, multiple patients with autoantibodies against TH-17 cytokines (comprising IL-17A, IL-17F, IL-22, IL-23) whose selective susceptibility to candidiasis strongly resembles inborn deficiencies with impaired production or response to IL-17 were described." (PMID 32419033, 2020). "Candidiasis often occurs in individuals with an inherited (gene mutations RORγ, RORγt, STAT3, TRAF3IP2, IL-17F, IL-17RA, IL-17RC) or acquired (drug-induced) dysregulation of IL-17." (PMID 40863217, 2025). "Congenital immunodeficiencies with candidiasis, T lymphocyte dysfunction, and IL-17 deficiency have been described in the context of pathogenic variants in genes such as STAT3, CARD9, DOCK8, ACT1, IL-17RC, IL-17RA, and IL-17F—where fluconazole is the first-line treatment." (PMID 40686918, 2025). "Interesting patterns of induction of the IL-17 family by Candida infection were observed; IL-17A was dependent on NLRC4, NLRP3 and ASC whereas IL-17F was only dependent on NLRP3 with comparable induction seen in WT, NLRC4 and ASC deficient mice." (PMID 22174673, 2011). "Comparisons of IL-17A and IL-17F generally indicate that IL-17A is more potent than IL-17F in mediating immunity to candidiasis, though this issue is still not fully defined." (PMID 25849644, 2015).
ulcerative colitis (10 papers, 2010 to 2025). An inflammatory bowel disease involving the mucosal surface of the large intestine and rectum. "T cell/ILC-associated genes most highly expressed in LPLs from infected Maffl/flCd4Cre mice, including IL17A and IL17F, were highly expressed in human IBD, again to a higher extent in ulcerative colitis." (PMID 38609547, 2024). "Inflammatory cytokines play crucial roles in the development of ulcerative colitis, as shown in DSS-treated mice, which presented significantly increased levels of inflammatory cytokines, including IL-1β, IL-23, and IL-17F, in colon extracts, whereas TNF-α levels were elevated in the serum." (PMID 40576745, 2025).
Obesity (8 papers, 2016 to 2025). Accumulation of substantial excess body fat. "This study established that the gain of miR-10a function has the potential to regulate the activity of both IL-17F and DC cells in obesity." (PMID 37334370, 2023). "Very little amount of literature is available on the role of IL-17F in obesity as it is simply described as a closely related cytokine of IL-17A." (PMID 32849611, 2020). "Lastly, we wanted to see if the treatment class, disease duration, obesity, alcohol consumption, smoking habit, or gender has an effect on serum levels of TNF-α, IL-17A, IL-17F, and IL-12/23 at the onset of treatment or after 12 weeks." (PMID 40699767, 2025). "Cytokines previously associated with increased inflammation, obesity, and metabolic diseases (IL-1β, IL-6, IFN-β, IL-1RA, and IL-17F) were numerically higher but not significantly different in mothers with obesity compared to mothers without obesity." (PMID 38068816, 2023). "Given that: (a) IL-17A has a causal role in multiple models of liver injury; (b) IL-17F shares a receptor with IL-17A; and (c) IL-17RA mice are protected from obesity-induced NASH, we hypothesized that both IL-17A and IL-17F signaling through IL-17RA is critical to NAFLD progression." (PMID 26895034, 2016).
osteoarthritis (8 papers, 2014 to 2023). A noninflammatory degenerative joint disease occurring chiefly in older persons, characterized by degeneration of the articular cartilage, hypertrophy of bone at the margins and changes in the synovial membrane. "Increased interleukin (IL)-17A has been identified in joints affected by osteoarthritis (OA), but it is unclear how IL-17A, and its family members IL-17AF and IL-17F, can contribute to human OA pathophysiology." (PMID 34054865, 2021). "In the doxorubicin-only treatment group, genes in the prolactin signaling pathway, the allergic inflammatory airway disease pathway by IL-17F, the Wnt/Ca2+ pathway, and the osteoarthritis pathway demonstrated significant gene expression changes." (PMID 33801927, 2021).
allergic asthma (7 papers, 2008 to 2021). A asthma with a basis in a pathological type I hypersensitivity reaction. "IL 17F is reported to be involved in inflammation and a study on effect of IL-17/IL-17F deficiency in an allergic asthma IL-17 KO mice model, exhibited reduced Th2 cytokine expression, whereas IL-17F KO mice showed elevated type 2 cytokines and eosinophil functions compared with WT mice." (PMID 22091390, 2011). "IL17F is expressed in human liver, lung, and fetal liver tissue and increased expression was oberserved in the airways of allergic asthma patients." (PMID 18197984, 2008). "It was reported that IL17F was expressed in bronchial epithelial cells and inflammatory cells in an allergic asthma mouse model but not in the lungs of control mice." (PMID 18197984, 2008).
hepatocellular carcinoma (7 papers, 2012 to 2025). A malignant tumor that arises from hepatocytes. "In contrast, IL-17F overexpression appears to inhibit tumor progression in experiments with human and mouse models of colorectal and hepatocellular carcinoma." (PMID 36422171, 2022). "In support of our results, over-expression of IL-17F in human hepatocellular carcinoma cells was reported with a decrease in tumor size and microvessel density in nude mice." (PMID 22509371, 2012). "A study of hepatitis C patients with liver fibrosis and hepatocellular carcinoma demonstrated that IL-17F expression was predominantly localized to hepatocytes, suggesting that serum IL-17F in these individuals may originate, at least in part, from hepatocyte-derived production." (PMID 41200179, 2025). "Subsequently IL-17F has successfully demonstrated direct inhibition of IL-6, IL-8, and VEGF expression of hepatocellular carcinoma (HCC) in vitro." (PMID 25110397, 2014).
leprosy (7 papers, 2013 to 2023). Leprosy is a chronic infectious disease affecting primarily the skin and peripheral nervous system. "In this study we aimed to identify the genotypic and allelic frequencies of IL-17A G-197A (rs227593) and IL-17F A7488G (His161Arg, rs763780) gene SNPs in the context of leprosy to identify if there was any association with susceptibility to leprosy in the Mexican Mestizo population." (PMID 25431761, 2014). "Both types of patients with reactional leprosy demonstrated a rise in IL-17A, IL-17F, and IL-22 levels." (PMID 37809252, 2023). "Both types of reactions are associated with significant increase of Th17 cells and associated cytokines IL-17A, IL-17F, IL-21, IL-23 and chemokines CCL20, CCL22 as compared to matching stable forms of leprosy." (PMID 27035913, 2016). "Distinct double positive IL17A and IL17F TH17 cells induce inflammation in patients with leprosy." (PMID 32516406, 2020). "However, antigen-stimulated-PBMCs from leprosy patients with the most severe form of the disease produced the highest amounts of IL17F." (PMID 31616423, 2019). "In leprosy, IL17F plasma levels are inversely proportional to the bacteriological index." (PMID 31616423, 2019). "Moreover, it was evidenced in leprosy that the bacteriological index was inversely correlated with the IL17F levels found in plasma." (PMID 31616423, 2019). "In conclusion, we identify lack of association of IL-17A G-197A (rs227593) and IL-17F A7488G (His161Arg, rs763780) gene SNPs with susceptibility to leprosy in Mexican population." (PMID 25431761, 2014). "That the IL-17 release was also influenced by the leprosy spectrum was indicated by BT patients who showed significant increase in expression of IL-17 isoforms: IL-17A (p<0.0002), IL-17C (p<0.003), IL-17D (p<0.003) and IL-17F (p<0.0001) as compared to the multibacillary LL patients." (PMID 23936569, 2013). "A rise in Th17 cells was seen in patients of both types of reactional leprosy in comparison to the non-reactional ones with identical symptoms, as demonstrated by the presence of IL-17F and IL-17A in CD4 cells." (PMID 37809252, 2023).
liver fibrosis (7 papers, 2015 to 2025). "In patients with mild liver fibrosis, liver steatosis was associated with lower serum concentrations of IL-13 and IL-17F." (PMID 39200991, 2024). "The importance of IL-17F in chronic hepatic diseases was poorly investigated; however, we had found Th-17 associated inflammatory cytokine, IL-17F, which took a major part in severe liver fibrosis and HCC symptoms in HCV patients than other inflammatory cytokines, IL-6, and IL-17A." (PMID 28770001, 2017). "It appears that IL-17F can be a precise biomarker for the diagnosis of liver fibrosis and HCC progression in the future." (PMID 28770001, 2017). "Due to HCC development is largely confined to patients with liver fibrosis and cirrhosis, a retrospective cohort study was further conducted to determine serum IL-17F expression levels in HCV patients with chronic hepatic diseases." (PMID 28770001, 2017). "Similarly, polymorphisms of the IL17 gene, particularly those affecting IL-17A and IL-17F, can influence the production of IL-17, a cytokine vital for mediating inflammation and liver fibrosis." (PMID 40332363, 2025). "Furthermore, the serum IL-17F levels were elevated in HCV-infected patients with severe liver fibrosis than in patients with mild liver fibrosis." (PMID 28770001, 2017). "The plasma levels of the IL17A cytokine (Kruskal–Wallis test, p = 0.02427), IL17F cytokine (Kruskal–Wallis test, p = 0.02575), and TLR4 (Kruskal–Wallis test, p < 0.0001) were significantly different among patients with various stages of liver fibrosis." (PMID 40332363, 2025). "In the present study, we evaluated the capacity of the BM-MSCs in the modulation of cytokines milieu and signal transducers, based on unique inflammatory genes Il17a and Il17f and their receptors Il17rc and their effect on the IL6/STAT3 pathway in CCl4-induced liver fibrosis in rats." (PMID 30346985, 2018). "The severity of liver fibrosis in HCV patients was associated only with IL-17F, but not with IL-17A, suggesting that IL-17F might be a better biomarker than IL-17A for HCV-associated fibrosis progression." (PMID 28770001, 2017).
plaque psoriasis (7 papers, 2021 to 2026). "Bimekizumab (BKZ), a monoclonal antibody targeting IL-17A and IL-17F, has shown high efficacy in plaque psoriasis." (PMID 42279028, 2026). "Bimekizumab, a novel biologic immunotherapy, exerts its therapeutic effect in plaque psoriasis by selectively neutralizing IL-17A and IL-17F." (PMID 41560729, 2025). "IL-17A and IL-17F are critical cytokines in the pathogenesis, especially in psoriasis vulgaris." (PMID 39519167, 2024).